CDK9 (cyclin dependent kinase 9)
Diseases named in the same sentence as CDK9 in open-access papers (continued):
Sharing a sentence is not in itself a finding about the gene and the disease.
chronic myeloid leukaemia (2 papers, 2020 to 2021). "For verifying whether erythroid differentiation associated with CDK9 on chronic myeloid leukemia cell lines and primary CML cells, we first constructed lentiviral recombinants expressing shRNA targeting CDK9 gene on K562 cells and evaluated knock down efficiency by using RT-qPCR." (PMID 34372855, 2021).
coronary artery disease (2 papers, 2021 to 2022). "The present work extends our knowledge of the kinase regulation in myocardial regeneration and indicates that targeting CDK9 and downstream signals might provide novel therapeutic implications in ischemic heart disease." (PMID 36082129, 2022).
coronary atherosclerosis (2 papers, 2016 to 2021). Atherosclerosis of the coronary vasculature. "Han Y. With colleagues found high concentrations of the CDK9 enzyme in patients with coronary atherosclerosis compared to the control group." (PMID 34948066, 2021). "We merit further investigation of CDK9 measurement in various clinical situations for identifying coronary atherosclerosis." (PMID 26636538, 2016).
developmental delay (2 papers, 2015 to 2019). "The recently identified homozygous CDK9 missense mutation p.(Arg225Cys) in three families with individuals affected by developmental delay, seizures, choanal atresia, eye coloboma or cataract and visual impairment as common features emphasizes P-TEFb to also play a role in human development." (PMID 31467394, 2019).
follicular lymphoma (2 papers, 2013 to 2015). Follicular lymphoma is a form of non-Hodgkin lymphoma characterized by a proliferation of B cells whose nodular structure of follicular architecture is preserved. "Abnormal mRNA levels of CDK9 and cyclin T1 have been found in Burkitt’s lymphoma, diffuse large B cell lymphoma with germinal center phenotype, classical Hodgkin’s lymphoma-derived cell lines, and follicular lymphoma." (PMID 25625291, 2015). "In addition, abnormal mRNA levels of CDK9 and cyclin T1 were found in Burkitt's lymphoma, diffuse large B cell lymphoma with germinal center phenotype, classical Hodgkin's lymphoma-derived cell lines, and follicular lymphoma." (PMID 23840966, 2013).
hypertrophic cardiomyopathy (2 papers, 2012 to 2022). A condition in which the myocardium is hypertrophied without an obvious cause. "CDK9 activity is upregulated in hypertrophic cardiomyopathy." (PMID 22458775, 2012).
inflammatory bowel disease (2 papers, 2022 to 2025). A spectrum of small and large bowel inflammatory diseases of unknown etiology. "Topological analysis identified 14 core targets based on centrality metrics, and five key intersection genes (CASP7, BIRC5, CDK9, STAT1, RELA) were highlighted as significantly associated with core network functions, including inflammatory bowel disease and apoptosis." (PMID 41515060, 2025).
lung adenocarcinoma (2 papers, 2021 to 2024). A carcinoma that arises from the lung and is characterized by the presence of malignant glandular epithelial cells. "Examination of the TCGA database show that CDK9 expression is elevated in lung adenocarcinomas and high expression of CDK9, SOX2, and SOX9 correlates with poor overall survival." (PMID 34359807, 2021). "Hence, we examined if CDK9 inhibitors can eliminate lung adenocarcinoma cells that are resistant to the third-generation EGFR inhibitor, Osimertinib, or the recently developed K-Ras G12C inhibitor, AMG510 (Sotorasib)." (PMID 34359807, 2021). "Additionally, results from the drug-resistant cells suggest that CDK9 inhibitors, alone or in combination with sublethal doses of BRD4 inhibitor, would be efficacious for patients who are burdened with K-Ras or EGFR mutated lung adenocarcinomas and those who have developed therapy resistance." (PMID 34359807, 2021).
medulloblastoma (2 papers, 2021). A malignant, invasive embryonal neoplasm arising from the cerebellum. "In medulloblastoma, CDK9 is highly expressed, and higher expression of CDK9 was shown to be correlated with poor patient prognosis." (PMID 34207158, 2021). "Furthermore, pharmacological inhibition of CDK9 by LDC067 in medulloblastoma cells and by TG02 (also referred to as zotiraciclib) in meningioma cells was found to suppress cell growth." (PMID 34207158, 2021). "Overall, these results offer a mechanistic implication of the transcriptional CDK9 and to a lesser extent of the cell cycle related CDK1 in the phenotypic effects observed after in vitro treatments with dinaciclib on medulloblastoma cells." (PMID 33686114, 2021).
midline carcinoma of NUT (2 papers, 2022 to 2024). "For example, CDK9 inhibition can disrupt transcriptional elongation, resulting from BRD4-NUT fusion proteins in NUT midline carcinoma, leading to cancer cell apoptosis." (PMID 38172923, 2024). "In midline carcinoma of NUT (NMC), BRD4 is hyperphosphorylated, and CDK9 was identified as the potential kinase that mediates BRD4 hyperphosphorylation." (PMID 35402244, 2022).
myeloid leukemia (2 papers, 2022). A clonal proliferation of myeloid cells and their precursors in the bone marrow, peripheral blood, and spleen. "In this context, CDK9 inhibitors are currently in clinical development in several hematologic malignancies such as myeloid leukemia or myelodysplastic syndrome." (PMID 35628286, 2022).
neutropenia (2 papers, 2022 to 2024). A decrease in the number of neutrophils found in the blood. "Still, most pan-CDK inhibitors targeting CDK9, such as flavopiridol, have produced undesirable toxicities in preclinical studies and/or clinical trials, including particularly concerning blood toxicities like neutropenia." (PMID 35442775, 2022). "The various nonspecific CDK9 inhibitors that have been tested in preclinical and clinical settings produce a range of toxicities and side effects that affect the stomach and liver and can also trigger hypokalemia and neutropenia." (PMID 35442775, 2022).
renal fibrosis (2 papers, 2017 to 2022). A final common manifestation of a wide variety of chronic kidney diseases characterized by glomerulosclerosis and tubulointerstitial fibrosis. "Cdk9 has been reported as a key molecule that promotes renal fibrosis in mice with unilateral ureteral obstructions." (PMID 28859164, 2017). "A recent study has shown that knockdown of CDK9 and a CDK9 inhibitor (LDC000067) could remarkably ameliorate renal fibrosis by blocking the phosphorylation of the Smad3 linker (Thr179)." (PMID 36313366, 2022). "In a mouse model of unilateral ureteral obstruction, CDK9 could also conjugate with Smad3 and Smad4 to form a complex to promote renal fibrosis." (PMID 36313366, 2022).
Retinal dystrophy (2 papers, 2021 to 2026). Retinal dystrophy is an abnormality of the retina associated with a hereditary process. "We consider the retinal dystrophy observed in our previous case and in the present case to be an essential phenotype associated with CDK9 variants." (PMID 40954203, 2026). "We concluded that CDK9 biallelic variants cause a CHARGE-like malformation syndrome with retinal dystrophy as a distinguishing feature." (PMID 33640901, 2021). "Thus, biallelic deficiency of CDK9 activity is now an established cause of a human multiple malformation syndrome that involves the eyes and features vision-threatening retinal dystrophy." (PMID 40954203, 2026). "Previously, we reported that an 8-year-old boy with the biallelic CDK9 variants p.A288T and p.R303C exhibited a CHARGE-like malformation syndrome in which retinal dystrophy was a distinguishing feature." (PMID 40954203, 2026). "The visual prognoses differ markedly between the two entities, in that retinal dystrophy is progressive in the CDK9-related disorder." (PMID 33640901, 2021). "In conclusion, CDK9 biallelic variants cause a CHARGE syndrome-like malformation syndrome with contracture of the fingers and retinal dystrophy as distinguishing features." (PMID 33640901, 2021). "In this study, we describe a female patient who also bears biallelic CDK9 variants but displays retinal dystrophy without a CHARGE-like malformation syndrome." (PMID 40954203, 2026). "We speculate that, depending on the impact on CDK9 kinase activity of a given CDK9 variant, retinal dystrophy with or without CHARGE-like malformation syndrome may occur." (PMID 40954203, 2026). "Thus, our study raises a possibility that retinal dystrophy can arise with or without a CHARGE-like malformation syndrome depending on the level of kinase activity associated with the combination of variant CDK9 alleles present." (PMID 40954203, 2026). "Thus, our study raises a possibility that phenotypic spectrum of biallelic CDK9 variants may extend to retinal dystrophy without CHARGE-like features." (PMID 40954203, 2026).
rheumatoid arthritis (2 papers, 2012 to 2016). A chronic, systemic autoimmune disorder characterized by inflammation in the synovial membranes and articular surfaces. "Furthermore, as inappropriate inhibition of neutrophil apoptosis contributes to chronic inflammatory diseases such as Rheumatoid Arthritis, CDK9 represents a novel therapeutic target in such diseases." (PMID 22276149, 2012). "Hence, CDK9 may be a good and specific target for neutrophil apoptosis, either as a short course of treatment in acute neutrophilic inflammation (e.g. acute respiratory distress syndrome), or for chronic diseases characterised by episodes of acute inflammation (e.g. rheumatoid arthritis)." (PMID 27833165, 2016).
Treacher-Collins syndrome (2 papers, 2021 to 2025). A congenital disorder of craniofacial development characterized by bilateral symmetrical oto-mandibular dysplasia without abnormalities of the extremities, and associated with several head and neck defects. "Treacher Collins syndrome is caused by defects of the polymerase II pathway which is regulated by CDK9, highlighting the importance of this pathway in syndromic hearing loss." (PMID 41191133, 2025). "Many of the syndromes characterized by multiple malformations, including Treacher Collins syndrome, are caused by defects in the polymerase II pathway, which is regulated by CDK9." (PMID 33640901, 2021).
urothelial carcinoma (2 papers, 2022 to 2023). A malignant neoplasm derived from the transitional epithelium of the urinary tract (urinary bladder, ureter, urethra, or renal pelvis). "In the TCGA cohort, high CDK9 expression correlated with longer overall survival and favorable clinical features of urothelial carcinoma." (PMID 36374405, 2023). "To determine the prognostic value of CDK9 expression in patients with urothelial carcinoma, we dichotomized the samples into low and high CDK9 expression groups, with the cutoff point being 219 H-score." (PMID 35326643, 2022). "As CDK9 has yet to be investigated as a therapeutic target in urothelial carcinoma, preclinical studies should be performed before attempting clinical trials." (PMID 35326643, 2022). "In this article, we investigated the prognostic role of cyclin-dependent kinase 9 expression in urothelial carcinoma." (PMID 35326643, 2022). "In this work, we explored the prognostic role of CDK9 expression in urothelial carcinoma." (PMID 35326643, 2022). "The decrease in CDK9 expression can be associated with the build-up of genetic instability and may indicate a key role for CDK9 in the early stages of urothelial carcinoma." (PMID 35326643, 2022). "High CDK9 expression has recently been associated with shorter patient survival time, but its role in urothelial carcinoma has not yet been explored." (PMID 35326643, 2022).
adenoma (1 paper, 2022). A neoplasm arising from the epithelium. "CDK9 and CDK18 were upregulated in NR5A1-adenomas, whereas CDK4 and CDK7 were upregulated in POUF1-adenomas." (PMID 35260162, 2022).
allergic rhinitis (1 paper, 2022). Inflammation of the nasal mucous membranes caused by an IgE-mediated response to external allergens. "The infiltration of inflammatory cells in OVA-induced experimental allergic rhinitis was appreciably diminished by miR-224 agomir, and this effect was associated with targeted inhibition of CDK9." (PMID 36184652, 2022).
cervical tumors (1 paper, 2022). "Therefore, Caspase-8 expression could be a marker in chemoresistant cervical tumors, suggesting CDK9 inhibitor treatment for their sensitization to Cisplatin-based chemotherapy." (PMID 36399280, 2022).
cholangiocarcinoma (1 paper, 2020). A carcinoma that arises from the intrahepatic biliary tree (intrahepatic cholangiocarcinoma) or from the junction, or adjacent to the junction, of the right and left hepatic ducts (hilar cholangiocarcinoma). "Furthermore, downregulation of EPIC1 leads to inhibition of Cyclin A and Cyclin D and CDK9 in cholangiocarcinoma cells." (PMID 32322669, 2020).
colitis (1 paper, 2022). Inflammation of the colon. "Systemic CDK9 inhibition resulted in an improved colitis score associated with diminished Th1 and Th17 cytokine production by colonic CD4+ T cells." (PMID 35660024, 2022). "Systemic CDK9 inhibition led to histological improvement of immune-mediated colitis and was associated with targeted suppression of colonic CD4+ T cell-derived IFN-γ and IL-17A." (PMID 35660024, 2022). "Together, these findings suggest that systemic CDK9 inhibition targets aberrant effector cytokine production at the site of inflammation and can be used to attenuate adaptive immune-mediated colitis." (PMID 35660024, 2022). "There was, however, an improvement in colitis scores in mice receiving systemic CDK9 inhibition, with the greatest effect observed with flavopiridol." (PMID 35660024, 2022). "In this study, we demonstrate that CDK9 inhibition supresses inflammatory cytokine production in an adoptive transfer colitis model and in colonic tissue from patients with IBD." (PMID 35660024, 2022). "In this study, we evaluated CDK9 inhibition in adaptive immune-mediated colitis and explored its effect on the transcriptional landscape and effector function of colonic CD4+ T cells from patients with IBD." (PMID 35660024, 2022). "The oral GSK3-α/β and CDK9 inhibitor, ABC1183, led to a dramatic improvement in dextran sulfate sodium- and 2,4,6-trinitrobenzene sulfonic acid- induced colitis that was associated with suppression of TNF-α and IL-6, and no observed organ or hematological toxicity." (PMID 35660024, 2022). "Next, we investigated whether CDK9 inhibition could directly suppress cytokine production in colonic explants from mice with established T cell transfer (TCT) colitis." (PMID 35660024, 2022). "Thus, TCT colitis represents an appropriate model to evaluate the response to CDK9 inhibition." (PMID 35660024, 2022). "In summary, using an immune-mediated murine colitis model and colonic lymphocytes from patients with IBD, we demonstrate the therapeutic potential of inhibiting P-TEFb/CDK9, a transcriptional elongation factor downstream of T-bet." (PMID 35660024, 2022). "Having established that CDK9 inhibition effectively suppresses IFN-γ and TNF-α production in CD4+ T cells, we reasoned that systemic delivery of CDK9i could abrogate experimental colitis." (PMID 35660024, 2022).
colorectal tumour (1 paper, 2019). "A preclinical xenograft model of HCT 116 human colorectal tumour validated the efficacy of CDKI‐73 and its CDK9 targeting effect in the tumour was confirmed." (PMID 31398271, 2019).
diffuse midline glioma (1 paper, 2022). A diffuse glioma that arises from the midline structures of the central nervous system. "More recently, H3K27M oncohistone-expressing diffuse midline gliomas (DMGs) have been shown to deregulate the expression of AFF4, a scaffolding protein involved in transcriptional elongation, which CDK9/CyclinT regulates." (PMID 35567477, 2022).
dysplasia (1 paper, 2025). A usually neoplastic transformation of the cell, associated with altered architectural tissue patterns. "The phosphorylation of p-RNA Pol II (Ser2) increased remarkably in moderate/severe dysplasia tissues and OSCC tissues, and the expression levels of CDK9 and p-RNA Pol II (Ser2) were positively correlated." (PMID 41360777, 2025).
esophagitis (1 paper, 2019). An acute or chronic inflammatory disease affecting the esophageal wall. "Regardless, studying the effects of this CDK9 inhibitor on radiation-induced esophagitis and toxicity to the peri-esophageal organs is warranted." (PMID 31384397, 2019).
fibrosis (1 paper, 2021). the formation of excess fibrous connective tissue in an organ or tissue in a reparative or reactive process. "Fibrosis is associated with upregulation of RBL1, CDK9, Renin receptor, mitogen-activated protein kinase p38α (Mapk14 gene)." (PMID 34428743, 2021).
HCMV infection (1 paper, 2016). "This concept has been substantiated by providing evidence for the high and multifaceted importance of CDK7 and CDK9 in HCMV infection." (PMID 27548200, 2016).
head and neck squamous cell carcinoma (1 paper, 2021). A squamous cell carcinoma that arises from any of the following anatomic sites: lip and oral cavity, nasal cavity, paranasal sinuses, pharynx, larynx, and salivary glands. "Another study conducted in head and neck squamous cell carcinoma (HNSCC) cell lines examined the relationship between CDK9, DNA damage, and sensitivity to radiation." (PMID 34207158, 2021).
hepatoblastoma (1 paper, 2023). Hepatoblastoma (HB) is a malignant hepatic tumor and is the most common pediatric liver cancer. "After deriving cell lines from the mouse model, we map cancer dependency genes using CRISPR-Cas9 screening and identify druggable targets shared with human hepatoblastoma (e.g., CDK7, CDK9, PRMT1, PRMT5)." (PMID 37414763, 2023).
influenza (1 paper, 2025). An acute viral infection of the respiratory tract, occurring in isolated cases, in epidemics, or in pandemics; it is caused by serologically different strains of viruses (influenzaviruses) designated A, B, and C, has a 3-day incubation period, and usually lasts for 3 to 10 days. "Our findings suggest that CDK9 might be a promising antiviral target, and LDC presents excellent potential as a novel anti-influenza candidate." (PMID 39565117, 2025). "Our findings suggest that CDK9 may be a promising antiviral target, and LDC has great potential as a novel anti-influenza agent." (PMID 39565117, 2025). "Altogether, our findings indicate that CDK9 could be a promising target for developing antivirals against influenza virus infections, and LDC, with its strong anti-influenza properties, instills confidence in its potential as an effective anti-influenza agent." (PMID 39565117, 2025).
injury (1 paper, 2015). Damage inflicted on the body as the direct or indirect result of an external force, with or without disruption of structural continuity. "Clearly, further understanding of the factors and pathways controlling CDK9 activity is required, and these pathways clearly merit further study as possible therapeutic targets to address diseases associated with acute and chronic heart injury." (PMID 26542022, 2015).
Intellectual disability (1 paper, 2021). "We report a male patient with multiple anomalies involving the eyes, ears, cleft lip, and palate, and intellectual disability and biallelic variants in the CDK9 gene in which one variant was derived from the mother and the other from the father." (PMID 33640901, 2021).